SNAI1 (snail family transcriptional repressor 1)
Diseases named in the same sentence as SNAI1 in open-access papers (continued):
Sharing a sentence is not in itself a finding about the gene and the disease.
cancer (continued). "Collectively, this study provides novel insight into the potential role of SNAI1 and SNAI2 in development and cancer metastasis." (PMID 20046880, 2009). "SNAI1 and SNAI2 are transcription factors that initiate Epithelial-to-Mesenchymal cell transitions throughout development and in cancer metastasis." (PMID 20046880, 2009). "This study found that SNAI1 had a higher CNV, consistent with previous findings that CNVs frequently occur in regions containing genes crucial for CRC, making them potential biomarkers for cancer detection." (PMID 40613523, 2025). "Snai1 and Slug disrupt cell-cell adhesion by inhibiting E-cadherin transcription, thereby regulating EMT, whereas reactive oxygen species activate Snai1 to promote cancer progression." (PMID 40881700, 2025). "We further found that, unlike in cancer cells where EGR1 promotes SNAI1/SNAIL expression, its downstream in normal mammary cells appears to be distinct." (PMID 40204777, 2025). "First, we found that ZEB1, SNAI1, SNAI2, TWST1, SMAD3, and HIC1, known to be affected upon EMT in both the RPE and forms of cancer, are preferential repressors in hiPSCs compared to RPE, likely acting as preventive developmental gatekeepers under physiological conditions." (PMID 40565279, 2025). "Normal A and cancer 0 clusters shared expression of heat shock protein A (HSPA) and insulin growth factor–binding protein (IGFBP) genes, engagement of the heat shock factor 1 signaling pathway, and activity of SNAI1, RUNX3, and TBX15 transcription factors." (PMID 40215177, 2025). "RBM47 is repressed by several EMT-related transcription factors, such as snail family transcriptional repressor 1 (SNAIL), snail family transcriptional repressor 2 (SLUG), signal transducer and activator of transcription 3 (STAT3), and SMAD family member 3 (SMAD3) in cancer cells." (PMID 41335176, 2025). "As a transcriptional repressor, SNAI1 is known for its ability to repress E-cadherin expression and promote the acquisition of a mesenchymal phenotype during EMT, a process that confers increased invasive and migratory properties to cancer cells." (PMID 38890750, 2024). "TFs like Snai1, Slug, and Twist1 have been demonstrated to be key regulators of EMT in carcinomas." (PMID 39095583, 2024). "Elevated expression of SNAI1 and SNAI2 have been observed in a variety of cancer types and correlate with increased risks of metastasis and postoperative relapse, predicting poor prognosis for the survival in cancer patients." (PMID 37596321, 2023). "For instance, the effects of Snai1 and ZEB1 on metastasis can vary depending on the type of cancer." (PMID 37444447, 2023). "E-cad transcriptional repressors Snail and SNAI1(Slug) induce invasiveness and CSC-like features and chemoresistance in ovarian cancer cells, suggesting that CSCs can be tackled by pharmacological inhibition of transcription factors that induce EMT in cancer." (PMID 37174052, 2023). "In the subsequent cell activity and apoptosis experiments, we found that the low expression of SNAI1, CDR2L, FRMD5, and FSTL3 could reduce the activity of cancer cells and increase the apoptosis rate of cancer cells." (PMID 36925652, 2023). "In cancer cell studies, SP1 was considered a key mediator of CYP1B1 action, whilst CYP1B1 was shown to activate a epithelial to mesenchymal transition and Wnt/beta-catenin-signaling pathways, upregulating beta-catenin and other TFs, such as ZEB2 and SNAI1." (PMID 37511270, 2023). "HOXD9 has been shown to promote cancer development via transcriptional activation of oncogenes, such as RUN and FYVE domain containing 3 (RUFY3), Snail family transcriptional repressor 1 (SNAI1), Sodium channel epithelial 1α subunit (SCNN1A) and Hemicentin 1 (HMCN1)." (PMID 36907878, 2023). "In the late stages of cancer, IL-6/STAT3 may promote the gain of invasive activity and the metastatic dissemination of cancer cells by inducing epithelial–mesenchymal transition (EMT) transcription factors (EMT-TFs), such as SNAI1 and TWIST." (PMID 36010693, 2022).
cancer (continued). "In malignant tumors, transcription factors like ZEB1 and ZEB2, SNAI1 and SNAI2, and Twist-related protein (TWIST) 1 and 2 may lead to migratory and invasive cancer cells." (PMID 35463825, 2022). "Finally, by considering the genes recapitulating IL-3 biological functions, we proposed a model, including IL-3Rα, SNAI1, ZEB1, VIM, CTNNB1, MMP2, SPRY2, and CD274, that remarkably discriminates cancer aggressiveness (AUC = 0.86 95% CI = 0.82–0.89)." (PMID 36010912, 2022). "In addition, we analyzed the correlation pair-wise (Pearson’s correlation test), between PEBP1 (RKIP) and SNAI1, VIM, CDH1/2, EPCAM, and LAMA1/B1 genes, across the 22 different types of cancer and normal tissues in the TCGA database." (PMID 36230521, 2022). "Furthermore, soluble factors derived from CH-hMSCs and PL-hMSCs also increased the expression levels of MYC, SNAI1, and TWIST, which play critical roles in the epithelial-mesenchymal transition and migration of cancer cells." (PMID 36406002, 2022). "SNAI1 expression level was no significantly different in primary cancer cells and non-cancer tissues." (PMID 35898399, 2022). "SNAI1 also induces MMP-14- and MMP-15-dependent BM transmigration by cancer cells." (PMID 35008569, 2021). "However, genes associated with cell differentiation (EPCAM, CK8, CK18, and FOXA2), EMT (SNAI1, FOSL1, and ID1), and cancer stem cells (CD44, CD133, ETV1, MALAT1, NEAT1, and NESTIN) displayed a more varied response compared to 2D cells." (PMID 33356003, 2021). "Moreover, FBXO45 inhibited cancer development and metastasis by targeting EMT-inducing transcription factors, including SNAI1/2, TWIST1/2, and ZEB1/2, in various cancer cells." (PMID 33966034, 2021). "Therefore, SNAI1 is usually regarded as one of the master transcription factors of EMT and a metastatic marker in cancer progression." (PMID 34718323, 2021). "For example, by immunohistochemistry analysis Ye and colleagues showed that the majority of mesenchymal cancer cells in this PyMT model were positive for the mesenchymal markers Zeb1 or Snai1, but not for fsp1." (PMID 34072345, 2021). "In multiple cancer types, including breast cancer, glioblastoma and melanoma, TGF-β signaling was maintained through canonical and non-canonical pathways and contributed to an upregulation of pro-EMT genes such as ZFGX1a, Slug and Snai1." (PMID 34072345, 2021). "Depletion of SNAI2 increases SNAI1 expression and vice versa; this compensatory regulation could be indispensable for EMT and cancer progression." (PMID 34681726, 2021). "Therefore, markers of EMT, such as vimentin, FN1, twist family bHLH transcription factor 1 (TWIST1), snail family transcriptional repressor 1 (SNAI1) and 2 (SNAI2, best known as SLUG) can be used to detect cancer dormancy." (PMID 33193295, 2020). "Additionally, CAFs have been reported to induce EMT in lung cancer and colorectal cancer by secreting exosomes containing SNAI1 and miRNAs such as mi-R21, respectively, that activate an EMT program in cancer cells." (PMID 32957515, 2020). "Furthermore, Twist1 expression positively correlates with EMT genes (CDH1, OCLN, TJP1, CDH2, FN1, SNAI1 and VIM) in various cancers." (PMID 32337580, 2020). "Furthermore, autophagy defects induced by the ATG7 knockdown significantly inhibited the degradation of SNAI1 in both cancer cell lines, indicating that ATG7-dependent autophagy is crucial for controlling the protein levels of SNAI1 in cancer cells." (PMID 30736337, 2019). "SNAI1, a transcription factor, is translocated into the nucleus where it inhibits the transcription of epithelial markers such as E-cadherin/CDH1 and promotes metastasis of most cancers." (PMID 30736337, 2019).
cancer (continued). "The low expression of RKIP/PEBP1 in cancer cells results in transcriptional and post-transcriptional modifications of proteins such as SNAI1 and NF-κB and consequently promotes the process of the epithelial to mesenchymal transition (EMT), which is an early step of cancer metastasis." (PMID 30115852, 2018). "Estrogenic induction of mesenchymal markers SNAI1, SNAI2, and CDH2 expression, with a consequent increase in cancer cell migration, was shown to depend on CXCR7, indicating a key role for CXCR7 in mediating estrogen upregulation of mesenchymal markers to induce invasion of OC cells." (PMID 30051594, 2018). "Although SNAI1 is a well-known gene involved in epithelial to mesenchymal transition in many cancers, it does not appear to be highly expressed in Ewing sarcoma tumors." (PMID 28148901, 2017). "A mesenchymal phenotype, characterised by low expression of E-cadherin (CDH1), high expression of vimentin (VIM) and high expression of EMT-inducing transcription factors, such as TWIST1, ZEB1, SNAI1 and SNAI2 moreover correlates with the expression of cancer stem cell markers CD44 and CD90." (PMID 29299154, 2017). "SNAI1, SNAI2, ZEB2, and VEGFA have been reported as miR-203 targets related to cancer invasion." (PMID 26882562, 2016). "Furthermore, the activity of aldehyde dehydrogenase (ALDH), a marker of cancer stem-cells, was increased by paclitaxel in HMLER cells by 1.27-fold and this effect was lost with knock-down of SNAI1." (PMID 26462028, 2015). "Here, we demonstrate that transcription factor glioma-associated oncogene 1 (GLI1) modulates EMT through direct up-regulation of SNAI1 and serves as a downstream effector of the transforming growth factor-β1 (TGFβ1) pathway, a well-known regulator of EMT in cancer cells." (PMID 23185371, 2012). "Moreover, our epithelial-to-mesenchymal transition (EMT) analysis revealed a consistent inverse association between PEBP1/STK11 co-expression and EMT marker genes, including SNAI1, SNAI2, FOXC2, ZEB1, and FN1, across most cancer types examined, thus underscoring a uniform anti-EMT signature." (PMID 40806276, 2025). "During such a reversion, cancer cells re-express several previously repressed genes, including those involved in cell plasticity (Oct4, SOX-2, and Nanog), while genes (PSEN1, Notch-1) and proteins (SNAI1, αSMA, N-cadherin) supporting epithelial–mesenchymal transition (EMT) are downregulated." (PMID 37511359, 2023). "In addition, we also analyzed the correlation between NUTF2 and the epithelial–mesenchymal transition (EMT) markers, Vimentin (VIM), TWIST1, Snail1 (SNAI1), Snail2 (SNAI2), Fibronectin 1 (FN1), and N‐cadherin (CDH2), which were widely accepted to be involved in cancer metastasis." (PMID 35155261, 2022). "EMT is also associated with invasion in new tissues, supported by the upregulation of Snail Family Transcriptional Repressor 1 (SNAI1) and Twist Basic Helix-Loop-Helix Transcription Factor 1 (TWIST1) via Snail Family Transcriptional Repressor 2 (SLUG; SNAI2) regulation in different cancer types." (PMID 35574343, 2022). "We uncover that JNK-mediated SNAI1 induction represents a negative feedback response that may counteract the natural anti-cancer agent and is involved in acquired resistance to triptonide in TNBC cells." (PMID 33510281, 2021). "SNAI1, a zinc finger transcription factor, not only acts as the master regulator of epithelial-mesenchymal transition (EMT) but also functions as a driver of cancer progression, including cell invasion, survival, immune regulation, stem cell properties, and metabolic regulation." (PMID 34681726, 2021). "Wnt/β-catenin signaling and expression patterns of important genes in cancer cell growth and survival, which were further suggested to play a role in three-dimensional aggregation, such as NFKB2, VEGFA, CTGF, CAV1, BCL2(L1), or SNAI1, were clearly affected by DEX." (PMID 32033410, 2020).
cancer (continued). "Moreover, upregulation of the Fn1, Mmp2, and Snai1 mRNAs, which are hallmarks of tube-forming growth in PDAC, was demonstrated in a mouse model of carcinogenesis showing rapid progression because of the aggressive invasion of tube-forming cancer." (PMID 31375695, 2019). "Among all PMFs, tangeretin was the most effective in targeting cancer stemness and self-renewal ability, whereas scutellarein tetramethylether was shown to modulate EMT-related markers (increasing CDH1 and reducing ZEB1 and SNAI1 expression) and highly synergistically interact with 5-FU." (PMID 30717428, 2019). "Mooney and co-workers showed that key regulators of EMT (e.g., ZEB1, SNAI1, and OVOL1/2) represent IDPs and hypothesized that it is their conformational flexibility which enables the formation of highly dynamic protein interaction networks and phenotypic plasticity of cancer cells." (PMID 40889682, 2025). "While changes in expression of TGF-β, ZEB1, SNAI1, MMPs, vimentin, and E-cadherin are hallmarks of an EMT process occurring within cancer cells, including cSCC cells, EMT within tissues is not an “all or none” process." (PMID 36012449, 2022). "ZEB1, ZEB2, SNAI1, and TWIST1 drive EMT of cancer cells, but they are not required for metastasis in animal models." (PMID 34339740, 2021). "The loss of SIK1 expression in epithelial-like phenotype MCF-7 cells promoted the expression of SNAI1, but did not significantly modulate its expression in MDA-MB-231 cancer cells already largely engaged in a mesenchymal phenotype." (PMID 31819138, 2019). "Most slides from cancer-free tissue lacked expression of CCND1, CD44, CDH1, EGFR, ERBB2, KIT, keratins, NOTCH1, PAK1, PTGS2, SNAI1, and VIM but showed staining of MUC1, HIF1A, NKX2-1, SFTPC, and STAT3, which were also found in AdCa." (PMID 23028920, 2012). "As a novel finding, we found that SNAI1-positive cancers also tend to home into the bone, whereas COX2-positive cancers do not." (PMID 21914172, 2011). "Although directly targeting SNAI1 seems not successful, the identification of PTM inhibitors toward SNAI1 has tremendous potential, and thus it is a high priority in the future development of cancer therapy." (PMID 39538371, 2024). "We showed that SNAI2 could recruit EZH2 but not SUZ12, suggesting SNAI1 and SNAI2 have different functions and non-overlapping roles in cancer cells and might cooperate to recruit PRC2 to the CDH1 promoter." (PMID 31938073, 2020).
infection (34 papers, 2013 to 2025). The state of being infected such as from the introduction of a foreign agent such as serum, vaccine, antigenic substance or organism. "Expression of SNAI1, which encodes for Snail1, a repressor of tight junction gene expression, was significantly increased with infection at the indicated time points." (PMID 36289516, 2022). "Mechanistically, HAstV-induced EMT is driven by transcriptional changes; specifically, the downregulation of CDH1 and OCLN and the upregulation of the key transcriptional factor SNAI1 early after infection." (PMID 35452499, 2022). "Here, we found that increasing multiplicity of infection (M.O.I.)amplified the effect of Salmonella treatment on the reduction of SNAI1 protein in mouse B16F10 and K1735 cell lines, with maximal efficiency at 100 M.O.I.." (PMID 34207850, 2021). "This indicates that T. cruzi upregulates the expression of both the transcript and the protein expression levels of SNAI1 in cardiac myocytes early during the process of infection." (PMID 26771187, 2016). "Interestingly, HV-HP infection was also associated with a reduction in CTNNB1 (catenin beta 1), and SNAI1 mRNA expression levels." (PMID 40642068, 2025). "Infection with H. pylori elevated USP35 and Snail Family Transcriptional Repressor 1 (Snail1) expression levels." (PMID 38893079, 2024). "The infection affected EMT indicators such as E-cadherin, N-cadherin, vimentin, and snail family transcriptional repressor 1 (SNAI1) expression and location." (PMID 38375155, 2024). "HRV16 infection also led to a significant increase in expression of genes involved in EMT (e.g., COL1A1, MMP9, SNAI1, and ZEB2) and growth factors (e.g., ~ fourfold for EGF and FGF2, and to a lesser extent TGFB1)." (PMID 34140575, 2021). "Interestingly, expression of OCLN was increased in hCMEC/D3s with infection, and we observed a tendency towards upregulation of TJP1 and CLDN5 together with downregulation of SNAI1 after 8 h of N. meningitidis infection." (PMID 36289516, 2022). "We showed that HAstV-VA1 failed to upregulate the transcription factor SNAI1 during a 24-hour infection." (PMID 35452499, 2022). "Our result showed that expression of SNAI1, N-cadherin and Vimentin was reduced in CoCl2-treated HCC cells after infection with Ad-shHIF1α, whereas E-cadherin was increased in CoCl2-treated HCC cells after infection with Ad-shHIF1α." (PMID 23496980, 2013). "The upregulation of SNAI1 was not sustained throughout infection but instead may be regulated in a biphasic manner as another increase in mRNA level was observed at 18 to 24 hpi." (PMID 35452499, 2022). "Furthermore, decreased expression of transcriptional factor (SNAI1, SNAI2) during pathogen infection may suppress VIM expression and reduce pathogen translocation into the cells." (PMID 34372621, 2021). "The mesenchymal marker vimentin/VIM was repressed by infection (FC, −2.22), whereas common markers of EMT (e.g., CDH1/2, SNAI1/2, and ZEB1/2) were not differentially expressed, suggesting that infection does not induce EMT in endocervical epithelial cells at 24 hpi." (PMID 37874141, 2023).
adenocarcinoma (7 papers, 2009 to 2021). A common cancer characterized by the presence of malignant glandular cells. "Heatmap analysis revealed upregulated VIM and PLK1 mRNA expression in TGF-β-treated adenocarcinoma when the mesenchymal markers CDH2, SNAI1, and SNAI2 were high and either CDH1 or OCLN (epithelial markers) was low in majority of LUAD cells analysed." (PMID 33963314, 2021).
kidney disease (3 papers, 2016 to 2021). "Interestingly, genes promoting EMT in kidney disease, Snai1, and Twist were significantly increased in Nedd4-2Ksp1.3 kidneys only after high Na+, suggesting that EMT may play a role in the severity of this disease." (PMID 33854040, 2021).
inflammation (1 paper, 2021). Aberrant reaction of the microcirculation characterized by movement of fluid and leukocytes from the blood into extravascular tissues. "Snail family zinc finger 1 (SNAI1/Snail) represents a transcription factor produced in various settings of kidney injury; SNAI1 modulates multiple biological events causing renal fibrogenesis, including destruction of cell adhesion, partial EMT of RTECs and renal interstitial inflammation." (PMID 33621200, 2021).
SNAI1 also shares sentences with these, for which no sentence is quoted: breast (10 papers); diabetes (8); endometriosis (7); renal carcinoma (7); fibrosis (6); Myocardial fibrosis (5); acute myeloid leukemia (4); Peritoneal Fibrosis (4); benign neoplasm (3); cholangiocarcinoma (3); embryonal rhabdomyosarcoma (3); gastric adenocarcinoma (3); gastrointestinal tumor (3); head and neck tumor (3); metastatic carcinoma (3); multiple myeloma (3); pulmonary hypertension (3); Sepsis (3); thyroid (3); adenomyosis (2); asthma (2); atrial fibrillation (2); colon adenocarcinoma (2); COVID-19 (2); dialysis (2); endometrioid ovarian cancer (2); malignant mesothelioma (2); non-alcoholic fatty liver disease (2); oral submucosal fibrosis (2); ovarian endometriosis (2).
A further 114 diseases each share a sentence with SNAI1 in 2 papers or fewer.